APOE (apolipoprotein E)
Diseases named in the same sentence as APOE in open-access papers (continued):
Sharing a sentence is not in itself a finding about the gene and the disease.
Alzheimer disease (continued). "His findings suggest that physical exercise is widely recognised for its positive impact on brain health, particularly among specific populations such as women with metabolic disorders and Alzheimer’s disease patients with the APOE-ε4 genotype." (PMID 41341725, 2025). "In Alzheimer’s disease cohorts with whole genome sequencing and tau and amyloid-β, the authors show that sex, APOE-ε4 and TREM2 impact tau via both Aβ and tau pathways." (PMID 40595476, 2025). "The deficiency of ABCA1 decreases cholesterol secretion to exogenous ApoE, leading to cholesterol accumulation in astrocytes and contributing to the occurrence of Alzheimer’s disease." (PMID 41303341, 2025). "Sleep duration and Apolipoprotein E genotype are critical factors influencing Alzheimer’s disease progression." (PMID 40994826, 2025). "Alzheimer’s disease is strongly linked to rare mutations in APP, PSEN1, and PSEN2 genes, while the APOE allele represents the strongest genetic risk factor for sporadic AD." (PMID 41143248, 2025). "The apolipoprotein E ε4 allele (APOE4), a significant genetic risk factor for Alzheimer’s disease (AD), has been linked to reduced Se levels and weakened antioxidant capacity." (PMID 39940451, 2025). "In Alzheimer’s disease models, SCFAs can increase amyloid-beta deposition and microglial-derived ApoE expression." (PMID 40809045, 2025). "Although previous studies have identified significant associations between the Alzheimer’s disease polygenic score and cognitive impairment in both European and African ancestries populations, some findings suggest that these associations may depend on the inclusion of the APOE locus." (PMID 41264616, 2025). "Compared to those with late-onset Alzheimer’s disease, patients with early-onset Alzheimer’s disease presented more severe impairment in language function, lower frequency of APOE ɛ4 and lower levels of plasma neurofilament light chain (all P < 0.05)." (PMID 39850631, 2025). "The apolipoprotein E ε4 allele (APOE4), a major genetic risk factor for Alzheimer’s disease (AD) and cognitive decline, has been implicated in impairments in lipid transport, amyloid-beta clearance, and neurovascular integrity." (PMID 40732946, 2025). "Critically, the expression of a specific APOE variant, APOE4, is the single largest genetic risk factor for the development of Alzheimer's disease and APOE4 homozygosity is now considered as a distinct form of genetic Alzheimer's disease." (PMID 40066661, 2025). "Our study demonstrates that Aβ pathology drives the upregulation of microglial GPC4 in Alzheimer’s disease which, in conjunction with APOE, amplifies tau pathology." (PMID 40883746, 2025). "All three studies performed pathway enrichment analyses to identify pathways related to lipid, cholesterol, and lipoprotein processing; amyloid pathways; tau; and immunity, which connect to the role of the APOE gene in lipid metabolism and Alzheimer’s disease." (PMID 40429722, 2025). "The frequency of APOE ε4 exceeds 40% among individuals diagnosed with Alzheimer’s disease but varies among populations—ranging from 9% to 20% in Caucasian, Japanese, African American, and Hispanic groups." (PMID 40869138, 2025). "This selection was made to scrutinize the influence of the APOE genotype on the modulation of the VAMP2/SYNTAXIN1/SNAP25 protein complex system within the brains of individuals with Alzheimer’s disease." (PMID 40003632, 2025). "Alzheimer disease (AD) has a strong genetic basis, yet previously derived polygenic risk scores (PRS) are heavily weighted by the APOE locus and perform inconsistently across diverse ancestries." (PMID 41040715, 2025). "In neurodegenerative disease therapy, liposomes conjugated with a modified ApoE-derived peptide were developed to target Aβ aggregates, facilitating drug delivery for Alzheimer’s disease treatment." (PMID 40286158, 2025).
Alzheimer disease (continued). "Data on diagnosis of glaucoma, diabetes, depression, Alzheimer’s disease, diabetic retinopathy, apolipoprotein E (APOE) E4 genotypes and data from ophthalmologic examinations were gathered." (PMID 40778276, 2025). "In Alzheimer’s disease, the thalamus and basal ganglia exhibit significant atrophy, and recent transcriptomic analyses have shown that genes such as APOE, MAPT, and PSEN1 are differentially expressed in these regions." (PMID 41142949, 2025). "Apolipoprotein E (ApoE) plays a critical role in Alzheimer’s disease (AD) by regulating amyloid beta (Aβ) clearance through direct interaction." (PMID 40892789, 2025). "Longitudinal investigation of the Apolipoprotein E (APOE) genotype’s impact on Alzheimer’s disease (AD) biomarker progression, focusing on amyloid beta (Aβ) accumulation and gray matter (GM) atrophy, integrating cognitive decline and baseline levels." (PMID 40167963, 2025). "In neurodegenerative diseases, particularly Alzheimer’s disease (AD), ApoE also influences protein aggregation and neuronal damage." (PMID 40362276, 2025). "APOE4, the major genetic risk factor for Alzheimer's disease (AD), and ABCA1, required for lipidation of APOE are gene products of the liver X receptor (LXR) receptor." (PMID 41000830, 2025). "Most prior studies on TREM2 and apolipoprotein E (ApoE) in Alzheimer's disease (AD) focus on experimental models, with limited computational work that primarily includes TREM2‐only models or short timescales." (PMID 40219843, 2025). "The apolipoprotein E (ApoE) ε4 allele and type 2 diabetes mellitus (T2DM) are independent risk factors for Alzheimer's disease (AD), the most prevalent neurodegenerative disorder in the elderly." (PMID 40905109, 2025). "Noninvasive and sensitive detection of tau protein dynamics across developmental stages and APOE genotypes remain a challenge in Alzheimer's disease (AD) research." (PMID 40444455, 2025). "APOE (apolipoprotein E) is a polymorphic protein, and the APOE ε4 allele is a well-established genetic risk factor for late-onset Alzheimer’s disease (AD), significantly increases the likelihood of developing AD." (PMID 41301354, 2025). "Participants with early Alzheimer's disease (AD) were stratified by apolipoprotein E (APOE) ε4 status and randomized (1:1:1) to receive low‐ or high‐dose aducanumab, or placebo." (PMID 40545559, 2025). "Apolipoprotein E (APOE) modifies human aging; specifically, the ε2 and ε4 alleles are among the strongest genetic predictors of longevity and Alzheimer’s disease (AD) risk, respectively." (PMID 40323280, 2025). "Lastly, the network contains a small ‘amyloid precursor protein’ community (purple) composed of Alzheimer’s disease (AD) genes cross-expressed with ApoE, which helps form amyloid plaques and neurofibrillary tangles." (PMID 39345494, 2025). "In this study, we investigated peripheral CHI3L1 expression across the Alzheimer’s disease (AD) spectrum, stratified by APOE genotype, age at onset (AAO), and sex." (PMID 41425914, 2025). "The Apolipoprotein E ε4 allele (APOE*4) is the strongest, common genetic risk factor for late-onset Alzheimer’s disease (AD), with one and two copies respectively increasing risk about 4 and 12-fold in European-ancestry populations." (PMID 41404291, 2025). "Isoform pairs in the APOE gene are often considered markers for the late development of Alzheimer’s disease." (PMID 39272762, 2024). "The dependent variable was brain age, and the independent variables were demographic (sex), health-related (Alzheimer’s disease stage), and neuroimaging (Abnormal Amyloid-β, APOE-ε4, and plasma neurofilament light)." (PMID 39518362, 2024). "APOE and APOC are well-described risk factors for numerous neurocognitive disorders (e.g., Alzheimer’s disease), and the APO ε4 variant was found to contribute to poorer cognition in PWH." (PMID 39283947, 2024).
Alzheimer disease (continued). "Apolipoprotein-E (APOE) genetic testing for Alzheimer’s disease is becoming more important as clinical trials are increasingly targeting individuals carrying APOE-ε4 alleles." (PMID 38167083, 2024). "The interactions of APOE ɛ4 and age were most prominent in the temporo-parietal lobes, which are known to be more vulnerable to early neurodegeneration and accumulation of Alzheimer’s disease abnormalities." (PMID 38384997, 2024). "APOE-ε4 (APOE4), a key genetic risk factor for Alzheimer’s disease (AD), is associated with altered connectivity in memory and cognitive networks, accelerated age-related connectivity loss, and sometimes increased hyperconnectivity 17–21." (PMID 39148839, 2024). "TREM2 also induces APOE signaling, and the APOE pathway mediates the change in microglial phenotype after phagocytosis of apoptotic neurons in mouse models of amyotrophic lateral sclerosis and Alzheimer's disease." (PMID 38362904, 2024). "Apolipoprotein E (APOE - gene; apoE - protein) is a 34 kDa lipid-transporting glycoprotein with three common isoforms conferring risk for Alzheimer’s disease (AD; risk ε2 < ε3 < ε4)." (PMID 35484240, 2024). "We included 286 subjects (135 controls, 108 Alzheimer’s disease dementia, 33 frontotemporal lobe dementia, and 10 vascular dementia) from the Amsterdam Dementia Cohort, with available neuropsychology, APOE, MRI and [18F]florbetaben amyloid-PET." (PMID 38768188, 2024). "The apolipoprotein E (APOE) gene has been studied due to its influence on Alzheimer’s disease (AD) development and work in an APOE mouse model recently demonstrated impaired respiratory motor plasticity following spinal cord injury (SCI)." (PMID 38748407, 2024). "ADAS, Alzheimer’s disease assessment scale; APOE4, apolipoprotein E 4; CDRS, clinical dementia rating scale; MMSE, mini-mental state examination." (PMID 38702626, 2024). "Females ApoE ε4 carriers are more likely to develop Alzheimer’s disease than male carriers and females have a faster rate in declining memory as compared to males." (PMID 39506641, 2024). "In this study, we investigated sex differences in relationships between BP, body mass index (BMI), and brain age over time and tested for interactions with APOE ε4 genotype (APOE4), a known genetic risk factor of Alzheimer disease." (PMID 39173100, 2024). "As a proof of concept, μLC-MS/MSanalysis of Alzheimer’s disease patient-derived iPSC cerebralorganoid reveals differential lipid metabolism depending on APOE phenotype(E3/3 vs E4/4)." (PMID 38113351, 2024). "Apolipoprotein E and Alzheimer's disease: the influence of apolipoprotein E on amyloid‐β and other amyloidogenic proteins." (PMID 39346788, 2024). "One such study explored APOE ε4 in 350 participants from the Knight ADRC (Alzheimer's Disease Research Center) study with flortaucipir PET and Aβ PET." (PMID 39293391, 2024). "The other interesting reason for this discrepancy is that carriers of apolipoprotein E (APOE) ε4 are at high risk for cognitive decline and Alzheimer’s disease." (PMID 39086905, 2024). "This infrastructure includes increased access to MRI and PET facilities, laboratory facilities to analyze CSF for Alzheimer’s disease biomarkers and testing blood APOE." (PMID 37592124, 2024). "Although nearly three decades have passed since the link between ApoE4 and Alzheimer’s disease was discovered, the mechanistic link between ApoE and AD is not well understood." (PMID 39596576, 2024). "In conclusion, we found that three genes (APOE, PICALM, and TSPOAP1) associated with Alzheimer’s disease in EA are also associated with measure of cognitive functions in South Asians living in India, with the association primarily driven by missense/LoF SNVs." (PMID 39149469, 2024). "APOE, a critical player in lipid metabolism and transport, has been extensively studied for its role in Alzheimer's disease (AD) and other neurodegenerative disorders." (PMID 38598053, 2024).
Alzheimer disease (continued). "APOE isoforms are biologically linked to neurodegenerative disorders, with APOE4 representing the highest risk factor of Alzheimer’s disease." (PMID 39449522, 2024). "Lastly, microglia express and release Apolipoprotein E (ApoE), a putative TREM2 agonist, and polymorphisms in the Apoe gene are a major risk determinate of Alzheimer’s disease." (PMID 38247852, 2024). "Apolipoprotein E (APOE) epsilon 4 is regarded as the most significant genetic contributor linked to mild cognitive impairment (MCI) and Alzheimer’s disease (AD)." (PMID 39639910, 2024). "We identified ligand-receptor pairs in three independent datasets and found involvement of the Alzheimer's disease risk genes APP and APOE across datasets." (PMID 38849813, 2024). "Atypical Alzheimer’s disease participants had a higher prevalence of APOE ɛ;4 carriers than CU individuals (P < 0.001), but a lower prevalence than amnestic Alzheimer’s disease participants (P = 0.003)." (PMID 38444909, 2024). "The Apolipoprotein E (APOE) gene has been well established in the Alzheimer’s disease (AD) literature to impact brain structure and function and modulate the risk for AD." (PMID 38635499, 2024). "Serrano-Pozo A., Das S., Hyman B.T. APOE and Alzheimer’s disease:advances in genetics, pathophysiology, and therapeutic approaches.Lancet Neurol." (PMID 38680184, 2024). "A brain region that is positively affected by long-term low-dose HRT is the HC in women expressing the ApoE-ε3/-ε4 genes, where HRT prevents from HC atrophy and is therefore also reducing the risk of developing Alzheimer’s disease." (PMID 39046467, 2024). "The interaction between complement C3 and APOE-ε4 leads to increased Alzheimer’s disease-related pathology." (PMID 38238858, 2024). "Nonetheless, some specific populations, such as women with metabolic disorders and Alzheimer’s disease patients with APOE-ε4 genotype, seem to be favorably affected." (PMID 38803456, 2024). "The APOE variant, rs7412, determines the APOE2 isoform, which has been shown in both human and animal studies to be protective against Alzheimer’s Disease and is additionally associated with longevity independent of Alzheimer’s Disease." (PMID 38969939, 2024). "This dysfunction was also associated with certain biomarkers, like the apolipoprotein E (APOE) ε4 allele, tau protein, and amyloid-β deposits, which were implicated in adverse health outcomes such as cardiovascular diseases, and Alzheimer’s disease." (PMID 39545350, 2024). "In this example, it is well known that the top SNP for Alzheimer's disease is the cis-SNP of the gene APOE located on chromosome 19 at position q13.32." (PMID 37953384, 2024). "Structure correctors are also being evaluated against the apoE, a protein bearing structural similarities to apoA-I, that is involved in the pathogenesis of Alzheimer’s disease." (PMID 38641010, 2024). "Given that our dataset included external controls from ADSP collected for Alzheimer's disease studies, there were potential selection biases for APOE ε4 and ε2 in controls." (PMID 39152475, 2024). "The heritability of late onset Alzheimer’s disease (LOAD) is estimated to be 60–80%, with Apolipoprotein E (APOE) ε4 allelic variants contributing the largest effect." (PMID 38230720, 2024). "Increasingly, data suggests that APOE ε4 heightens the likelihood of Alzheimer’s disease development through amplified toxic impacts and diminished protective capabilities." (PMID 39639910, 2024). "Targeting APOE and lipid metabolism in microglia represents a promising therapeutic strategy for Alzheimer’s disease." (PMID 39612244, 2024). "The genomic region 19q13.32 where gene APOE is located has also been related to Alzheimer's disease and schizophrenia." (PMID 38190638, 2024). "TWASs of Alzheimer’s disease have discovered dozens of “causal” tissue-specific genes, such as ACE, APOE, APOC1, FAM241A, SAPCD1, FAM111A, and TOMM40." (PMID 38542318, 2024).
Alzheimer disease (continued). "Sex and APOE ε4 genotype play a crucial role in modulating cognitive outcomes and depression in various neurological conditions like Alzheimer's disease." (PMID 39886338, 2024). "APOE functions as a lipid transport protein with a crucial role in the central nervous system, and its significance and functions in the context of Alzheimer’s disease have been extensively documented in numerous research studies." (PMID 38627829, 2024). "No changes were found in the EQ-5D-5L, whereas the patient-reported Quality of Life in Alzheimer's Disease (QoL-AD) showed a significant improvement in subjective quality of life for APOE-positive participants in the intervention group (+1.5/−0.0p, p=0.042)." (PMID 38715705, 2024). "In this study, we report a novel approach to modeling APOE ε4 Alzheimer’s disease (AD) using 3D induced brain organoids directly converted from AD patient fibroblasts." (PMID 39185458, 2024). "Since ApoE, particularly lipidated ApoE, mediates the clearance of β-amyloid (Aβ), the canonical driver of Alzheimer’s disease (AD), LXRs have received significant attention in this neurological condition." (PMID 38627787, 2024). "The ε4 allele of the apolipoprotein E gene (APOE4) is expressed abundantly in both the brain and peripheral circulation as a genetic risk factor for Alzheimer’s disease (AD)." (PMID 38628697, 2024). "Apolipoprotein (APOE) ɛ4 positivity and subjective cognitive decline (SCD) both increase risk of Alzheimer’s disease (AD) development." (PMID 38253819, 2024). "Clinical, APOE genotype, and cerebrospinal fluid (CSF) proteome and AD biomarker data was sourced from the Alzheimer's Disease Neuroimaging Initiative (ADNI) database." (PMID 39722190, 2024). "The apolipoprotein E (APOE) gene, especially the ε4 allele, is a well-established genetic risk factor for Alzheimer's disease (AD) and other NCDs." (PMID 39364454, 2024). "The apolipoprotein E gene (APOE) is an established central player in the pathogenesis of Alzheimer's disease (AD), with distinct apoE isoforms exerting diverse effects." (PMID 39031528, 2024). "The role in inverse comorbidity of cancer and Parkinson’s disease/Alzheimer’s disease was shown for APOE, APOC1, SQSTM1, PSEN1, and SP1." (PMID 37298337, 2023). "APOE is mainly synthesized in the liver, but most research is being performed on the role of APOE in the brain, since APOE4 is an independent risk factor for Alzheimer’s disease and age-related mortality." (PMID 36749362, 2023). "Our findings suggest that interactions between ApoE and COMT are found in cognitive domains typically associated with Alzheimer’s disease and are less related to factors related to healthy cognitive and motoric aging broadly." (PMID 37744392, 2023). "APOE has three isoforms, i.e., APOE2, E3, and E4, of which E4 is known as a risk gene for Alzheimer’s disease, multiple sclerosis, and other neurodegenerative disorders." (PMID 38201273, 2023). "The various ApoE isoforms differ in their ability to bind lipids and amyloid-β, a critical protein in Alzheimer’s disease." (PMID 36980195, 2023). "CLU is now considered the third greatest risk gene for late onset Alzheimer’s disease (LOAD), after APOE and BIN1." (PMID 37047762, 2023). "Research has demonstrated that APOE, a protein found in the brain, plays an integral role in Alzheimer’s disease by its interaction with amyloid-beta protein." (PMID 37445986, 2023). "Early identification of Apolipoprotein E (APOE)-related microvascular pathology will help to study the microangiopathic contribution to Alzheimer’s disease and provide a therapeutic target for early intervention." (PMID 37685715, 2023). "All three of the replicated genes have been previously associated with clinically diagnosed Alzheimer’s disease (SORL1, TREM2, and TOMM40/APOE)." (PMID 36750708, 2023). "A T→C SNP at the GC-rich apolipoprotein E (APOE) region is known to vary G4 structure and has been linked to the onset of Alzheimer’s disease." (PMID 38136947, 2023).